PARP10 (poly(ADP-ribose) polymerase family member 10)
Diseases named in the same sentence as PARP10 in open-access papers (continued):
Sharing a sentence is not in itself a finding about the gene and the disease.
Immunodeficiency (1 paper, 2023). Failure of the immune system to protect the body adequately from infection, due to the absence or insufficiency of some component process or substance. "But, because many genes in this subnetwork are immunodeficiency-related, we believe that PARP10 has a higher likelihood of being associated with immunodeficiency." (PMID 38113079, 2023).
lymph node metastasis (1 paper, 2022). "Correlation analysis showed that high PARP10 expression was significantly associated with several malignant features, including histological differentiation (p < 0.001), lymph node metastasis (p < 0.05) and clinical stage (p < 0.01)." (PMID 36313419, 2022). "Moreover, increased PARP10 protein levels were correlated with several clinicopathologic indicators, including histological differentiation, lymph node metastasis, and clinical stage." (PMID 36313419, 2022).
tumor (26 papers, 2015 to 2026). "Xenotransplantation studies in mice have shown that PARP10/ARTD10 deficiency inhibits the growth of HeLa cells and that PARP10 overexpression promotes tumor progression." (PMID 41326692, 2026). "In this study, PARP10 deficiency was shown to promote tumor cell migration and invasion via MARylation of the Aurora A protein." (PMID 36814782, 2023). "PARP10 has been implicated in various biological processes, including the regulation of cancer cell proliferation and tumor metastasis." (PMID 36313419, 2022). "PARP6 and PARP10: This ambiguous role in tumor repression and progression is also observed in PARP6 and PARP10." (PMID 41463260, 2025). "The loss of the monADP‐ribosyltransferase PARP10 significantly increases tumor migration and invasion by regulating epithelial–mesenchymal transition (EMT), and its tumor‐suppressive function in metastasis depends on its enzymatic activity." (PMID 40904702, 2025). "PARP10 expression promotes replication fork stability and inhibits replication stress, thereby promoting cell proliferation in vitro and tumor growth in vivo." (PMID 40904702, 2025). "Gene expression profiling confirmed increased expression levels of other members of the ARTD family including Parp9, Parp10, Parp12 and Parp14 in Parp7KO tumours." (PMID 39867896, 2024). "Overall, although with different outcomes, dysregulation of PARP10 appears to be central in tumour progression, determining specific biological consequences strictly dictated by the cellular context and the substrates involved." (PMID 39189367, 2024). "Following this discovery, a potent PARP10 inhibitor, A82-(CONHMe)-B354, has also been developed, although further research is needed to determine its efficacy against tumor cells and its role as a future therapeutic agent." (PMID 37508568, 2023). "Despite PARP10’s role in overcoming replication stress, it has also been shown to quell tumor metastasis through the regulation of cell migration." (PMID 37508568, 2023). "Subsequent MARylation of Aurora A by ubiquitinated PARP10 suppressed its kinase activity and downstream signaling, negatively impacting tumor metastasis." (PMID 36814782, 2023). "The mono-ADP-ribosyltransferase PARP10 is frequently amplified in different tumor types, and has been shown to promote in vitro cellular proliferation and in vivo tumoral growth." (PMID 36358629, 2022). "Supporting this assertion, PARP10 depletion significantly inhibited tumour growth in a mouse xenograft model." (PMID 35096828, 2021). "In other cases, such as PARP6 and PARP10, there is controversy as to whether we are dealing with a role in tumor repression and progression." (PMID 41463260, 2025). "This role correlates with PARP10 overexpression in a large proportion of human tumours, where it promotes cellular transformation, potentially by alleviating cellular sensitivity to replication stress and favouring the restart of stalled replication forks (Refs 21, 22)." (PMID 39189367, 2024). "Subsequent studies showed that PARP10 can function as either a tumor suppressor or an oncogene." (PMID 36313419, 2022). "Given that PARP10 has a role in DNA repair and its depletion inhibits tumour growth, it is suggested that it may be a chemotherapeutic target." (PMID 35096828, 2021). "We assessed cellular proliferation upon the ablation of PARP10 in the four tumor cell lines." (PMID 29293500, 2018). "At the initial stage of tumorigenesis, these mutated genes might be tumor-initiating SNVs in conjunction with the CNAs of FAT1, MYC, PARP10, and CYC1." (PMID 30143682, 2018). "PARP10 is a MYC-interacting protein that plays a tumor-suppressive role." (PMID 26735889, 2016). "Notably, PARP4, PARP7, PARP10, PARP11, and PARP15 have been clearly implicated in tumor development and progression, functioning either as oncoproteins with prognostic relevance or, in certain contexts, as tumor-suppressive factors." (PMID 41463260, 2025).
tumor (continued). "In other tumours, PARP10 deficiency correlates with an increase of cancer cell proliferation and migration: in this context, absence of PARP10 results in a reduced MARylation of the substrate Aurora A causing an increased cancer cell invasion and migration, without affecting cell-cycle progression." (PMID 39189367, 2024). "Consequently, from these two sets of data, it could be concluded that PARP10 acts differently on Aurora-A depending on the specific cell process (e.g., tumor spreading vs. cell cycle regulation), leading to the specific regulation of different functions." (PMID 36358629, 2022). "PARP10 can inhibit Aurora A activity by interacting with it and mono-ADP-ribosylating it, which leads to inhibition of tumor metastasis." (PMID 36313419, 2022). "Recently, we found that PARP10, another mono-ADP-ribosyltransferase, suppresses tumor metastasis dependent on the MARylation of Aurora A by PARP1039." (PMID 30154409, 2018). "Additionally, PARP10 overexpression in the non-transformed cell line RPE-1 resulted in significant tumor growth in xenograft mouse studies, suggesting oncogene like properties." (PMID 36814782, 2023). "In addition, forced expression of PARP10 is sufficient to induce tumor formation by non-transforming RPE-1 cells." (PMID 36313419, 2022). "PARP10-Aurora A interaction did not impact its role in cell cycle, but it did regulate its role in EMT, suggesting a role for PARP10 in mediating migration and invasion of tumor cells." (PMID 36814782, 2023).
cancer (20 papers, 2017 to 2026). A tumor composed of atypical neoplastic, often pleomorphic cells that invade other tissues. "PARP10 is involved in regulating cellular autophagy in cellular models; in a cell cancer model, loss of PARP10 induces fatty acid oxidation." (PMID 36635413, 2023). "PARP10 has been demonstrated to be involved in cancer progression via regulation of the PI3K-AKT signaling pathway." (PMID 41326692, 2026). "In 2017, a race began to develop catalytic inhibitors of PARP10 in order to describe their physiological implications in greater detail, as well as to use them in models of neurodegeneration and cancer." (PMID 41463260, 2025). "Given their recently discovered roles in cancer development and response to chemotherapeutics, PARP10 and PARP14 represent promising clinical targets." (PMID 36814782, 2023). "Here, we summarize the current knowledge on MARylation in DNA repair and cancer, focusing on PARP10 and PARP14." (PMID 36814782, 2023). "For the PARP10-overexpressing screen, we decided to employ the non-cancer breast epithelial cell line MCF10A." (PMID 36187556, 2022). "Our work identifies a network of functionally relevant PARP10 synthetic interactions, and reveals a set of factors which can potentially be targeted in personalized cancer therapy." (PMID 36187556, 2022). "Our work reveals novel PARP10 genetic interactions of functional relevance and identifies a set of factors which can potentially be targeted in personalized cancer therapy." (PMID 36187556, 2022). "Our data support that PARP10 is necessary for cellular proliferation, however add that the effects of PARP10 appears to be tissue/cancer dependent." (PMID 29293500, 2018). "Taken together in cancer and metabolic models PARP10 expression was regulated inversely as mitochondrial oxidative capacity." (PMID 29293500, 2018). "PARP10-mediated AMPK activation can modulate metabolic adaptation in cancer cells and in different metabolic tissues upon fasting." (PMID 29293500, 2018). "Based on these findings, we reasoned that BRCA deficient cells may be hyper-reliant on PARP10-mediated gap filling, thereby providing a window of opportunity for therapeutic intervention in BRCA-mutant cancers." (PMID 39043663, 2024). "Despite having strong link to various pathogenic states such as inflammatory diseases and cancer, PARP10 and PARP14 inhibitors have not been well characterized." (PMID 36814782, 2023). "The authors also probed datasets to show that PARP10 is amplified in a variety of cancers, and hence a role as a putative oncogene was hypothesized." (PMID 36814782, 2023). "Finally, since both PARP10 and PARP14 represent potential targets for cancer therapy, extensive characterization of PARP10 and PARP14 inhibitors in clinical settings is needed to determine therapeutic efficacy of these inhibitors." (PMID 36814782, 2023). "Interestingly, PARP10 overexpression is commonly seen in cancers due to its role in the alleviation of replication stress, with the appearance of longer replication tracts noted under both control and Hydroxyurea-treated cells." (PMID 37508568, 2023). "Our results suggest that inhibition of this complex may be combined with PARP10 inhibition for reducing the proliferation of cancer cells." (PMID 36187556, 2022). "On the otherhand, PARP10 overexpression in various cancer cell lines along withthe known PARP10 target proteins led to the hypothesis that PARP10promotes cancer proliferation and acts as an oncogene." (PMID 35608571, 2022). "In parallel, the relevance of PARP10 catalytic activity in regulating cell-cycle progression was evaluated by analyzing the extent of mitosis in HeLa cells as well as in additional cancer cell lines, all expressing comparable levels of PARP10 protein, upon PARP10 inhibitor treatment." (PMID 36358629, 2022). "PARP6 and PARP10 have both promoting and suppressive effects on cancer development." (PMID 34976832, 2021).
cancer (continued). "Interestingly, all cancers with PARP10 amplification also showed co-occurrence of REQL4 amplification, similar to the co-occurrence profile seen in the cell lines Kuramochi and COV362." (PMID 33804647, 2021). "Identifying how MARylation regulates these substrates, and the changes in binding partners induced by the modification, is likely to reveal critical mechanisms employed by PARP10 and PARP14 in cancer." (PMID 36814782, 2023). "Chiefly among those is the identity of the relevant substrates of PARP10 and PARP14 in genome stability and cancer cell proliferation and tumorigenesis." (PMID 36814782, 2023). "Here, we highlighted the roles of MARylation, and in particular those of PARP10 and PARP14, in DNA repair and cancer." (PMID 36814782, 2023). "Here, we outline some of the key roles of PARP10 and PARP14 in modulating DNA damage repair, and how PARP10/PARP14 status affects cancer development and the response to chemotherapeutics." (PMID 36814782, 2023). "We highlight the roles of PARP10 and PARP14 in cancer progression and response to chemotherapeutics and briefly discuss currently known PARP10 and PARP14 inhibitors." (PMID 36814782, 2023). "Here, we showed that two pathways critical for cancer cell proliferation and metastasis, the PI3K-AKT and MAPK signaling pathways, were hampered by silencing PARP10." (PMID 36313419, 2022). "Recent developments in enzymatic approaches to obtain ADP-modified peptides by PARP6, PARP3, PARP14, and PARP10 in human and murine diseases are advancing our ability to generate site-specific MAR antibodies, with future application in animal models of cancer and neurodegenerative diseases." (PMID 41463260, 2025). "PARP10 regulates the MYC-induced transcription, influencing genes involved in cell cycle, proliferation, and differentiation, consequently playing a key role in several cancers." (PMID 41463260, 2025). "In addition, the regulation of PARP10 and PARP14 activity in normal and cancer cells, as well as the mechanisms of their subcellular localization, particularly their recruitment to DNA, is of significant interest." (PMID 36814782, 2023). "Recently, the physiological role of PARP10 in cancers has begun to be understood; however, to date, neither the clinical significance of PARP10 nor the function and downstream of PARP10 in OSCC has been clarified." (PMID 36313419, 2022). "Moreover, PARP10 has also been revealed to modulate mitochondrial oxidative metabolism via regulation of AMPK, thereby affecting cancer cell proliferation." (PMID 36313419, 2022). "We proposed that PARP10 overexpression during transformation allows suppression of replication stress through TLS-mediated bypass of replication arresting structures, thereby allowing hyper-proliferation of cancer cells." (PMID 36187556, 2022). "Furthermore, we analyzed our original chromatin accessibility data,and found that the DNA binding motifs of ELF1, JUND, and SPI1, which arepotential transcription factors of PARP10, NIPAL1 and ZYG11B in CRC tissues, arespecifically open in cancer tissues compared with adjacent tissues." (PMID 41020586, 2025). "Since PARP10 inhibitors are currently being developed, we reasoned that this screen may result in the identification of new targets for cancer therapy in combination with PARP10 inhibition, regardless of the PARP10 overexpression status." (PMID 36187556, 2022).
infection (8 papers, 2011 to 2026). The state of being infected such as from the introduction of a foreign agent such as serum, vaccine, antigenic substance or organism. "Uncovering this novel bacterial survival mechanism not only deepens our understanding of the infection process but also reveals the PARP10 pathway as a promising new target for developing much-needed therapeutic drugs against this pervasive pathogen." (PMID 42165671, 2026). "A core of interferon-related proteins was detected in all infections at 72 hpi, although expression of XAF1 and PARP10 was also detected only after infection with IC89." (PMID 34671358, 2021). "After host cells were decided, we explored the effect of BHK21 cells on virus proliferation through PARP10 over expression or knock-down, with 48 h after the infection as starting point of the detection." (PMID 22176891, 2011). "PARP10 can also inhibit the activation of NF-κB which is activated during infection." (PMID 31216043, 2019). "Therefore, we chose BHK21 cells and 48 h after infection to investigate the effect of PARP10 on AIV proliferation." (PMID 22176891, 2011). "Overexpression of PARP10 and PARP12 decreased EGFP expressing cells as measured by flow cytometry 24 and 48 h post-infection (hpi)." (PMID 36840772, 2023). "We found members of this family upregulated by both VN1203 and BC500 infection in ducks (PARP9, PARP10, PARP12 and PARP14)." (PMID 34804075, 2021).
PARP10 also shares sentences with these, for which no sentence is quoted: colorectal carcinoma (2 papers); heart failure (2); acute myeloid leukemia (1); bladder cancers (1); chronic myeloid leukemia (1); glioblastoma (1); lung carcinoma (1); metastatic tumor (1); myeloma (1); myocardial infarction (1); neurodegenerative disease (1); neuropathy (1); osteosarcoma (1).